CCL2 (C-C motif chemokine ligand 2)
Diseases named in the same sentence as CCL2 in open-access papers (continued):
Sharing a sentence is not in itself a finding about the gene and the disease.
COVID-19 (continued). "Monocytes of HD + COVID-19 patients secreted significant higher levels of the pro-inflammatory cytokines GM-CSF, IL-1β, IL8, IL-10, CCL2 and CCL3 compared to non-infected HD patients." (PMID 36675231, 2023). "Remarkably, COVID-19 patients requiring intensive care unit (ICU) admission presented higher levels of CCL2, CXCL10, IL-2, IL-7, IL-10 and TNF-α than non-ICU patients, hinting the linkage between the cytokine storm and COVID-19 deterioration." (PMID 37251383, 2023). "Megakaryocytes can also contribute to inflammatory signaling however no upregulation of inflammatory-related genes (e.g., CCL2, CLL3, IL-6 and CXCL8, etc.)were observed in the megakaryocytes from COVID-19 patients including those with encephalopathy." (PMID 37848421, 2023). "Genes activated in the ‘no prior infection’ cohort, such as CCL2 and USP18, are part of the interferon response in severe COVID-19." (PMID 35441161, 2022). "COVID-19 patients show higher concentrations of IL-2, IL-7, IL-10, G-CSF, IP10 (CXCL10), MCP-1 (CCL2), MIP1a (CCL3) and TNF-α than non-COVID-19 patients." (PMID 35901034, 2022). "Results showed that compared with patients with less severe infections without Intensive Care Unit (ICU), patients with COVID-19 with ICU had higher concentrations of CXCL10, CCL2, and TNF-α." (PMID 35911765, 2022). "Mostly, markers of inflammation such as IL-6, IL-10, CXCL10 (also known as IP10), CXCL11, CCL2, CCL7, CCL8, PD-L1, and IL-18R1 were increased at the early stage of COVID-19 in ICU patients compared to non-ICU ones." (PMID 35269564, 2022). "Considering the objectives of our study, we highlight that there were significant, direct correlations between CCl2, galectin-3, PON1 concentration, CRP, IL-10, IL-6, and angiotensin II in COVID-19 positive patients, but not in the COVID negative ones." (PMID 34205807, 2021). "In contrast, MCP-1/CCL2 and MIP-1β/CCL4 were elevated selectively in patients who eventually succumbed to COVID-19 but not in those with milder illness." (PMID 33232303, 2021). "This corroborates with our data where, contrary to CCL2, serum CX3CL1 was quicky augmented suggesting that non-classical monocytes (NC; CD14+/-CD16++/CX3CR1+) rather than classic monocytes (CL; CD14++CD16−/CCR2+) are the first actors during COVID-19." (PMID 40710346, 2025). "One of the first studies to evaluate the serum cytokine storm in COVID-19 patients showed that several pro-inflammatory mediator levels, such as TNFα, IL-2, IL-7, IL-10, G-CSF, CXCL10, CCL2 and CCL3, were increased in ICU (n = 13) compared to non-ICU COVID-19 patients (n = 28)." (PMID 36941580, 2023). "In COVID-19 non-survivor genes related to neutrophil chemotaxis and migration, including CXCL10, CCL20, CCL8, C3AR1, CCL2, VAV3 are significantly upregulated; increased neutrophil is a typical signature of COVID-19 and closely linked to fatality, as already reported by other studies." (PMID 37949875, 2023). "The cytokine storm has already been attenuated following recovery from COVID-19, as levels of TNF-α, free active TGF-β, IFN-γ, IL-1β, IL-2, IL-4, IL-6, IL-8, IL-10, IL-12p70, IL-17 and MCP-1/CCL2 during convalescence were not higher compared to healthy volunteers." (PMID 35757700, 2022). "Concentrations of select chemokines (CXCL8, CXCL10, CCL2, CCL3, CCR1) and complement factors (C2, C9, CFD, C4BPA, C5AR1, CR1) were examined at mRNA and protein levels with regard to a COVID-19 course (ICU vs. non-ICU group) and CMV status at different time intervals." (PMID 36232655, 2022). "Clinical evaluation of 41 COVID-19 patients (Non-ICU: 28 and ICU: 13) for over 26 chemokines and cytokines revealed increased levels of 16 of them such as IL-1β, IL-1RA, IL-17, IL-8, IL-9, IL-10, basic FGF, G-CSF, GM-CSF, IFN-γ, CXCL10, CCL2, CCL3, CCL4, PDGF, TNF-α." (PMID 33335518, 2020).
COVID-19 (continued). "Critically ill COVID-19 patients exhibited an increased ratio of white blood cells/lymphocytes and higher plasma levels of C-reactive protein (CRP), IL-2, IL-7, IL-10, GSCF, IP10 (CXCL10), MCP-1 (CCL2), MIP-1α (CCL3), and TNF-α, as compared to non-ICU patients." (PMID 32998763, 2020).
atherosclerosis (866 papers, 2005 to 2026). A disease characterized by the build-up of fatty material and calcium deposition in the arterial wall resulting in partial or complete occlusion of the arterial lumen. "Our findings extend our previous results from a Mendelian randomization study suggesting a higher atherosclerosis risk among individuals with genetic predisposition to elevated CCL2 levels." (PMID 40119478, 2025). "Experimental evidence indicates that CCL2 deficiency is linked to a significant decrease in arterial lipid deposits, while elevated levels of CCL2 are associated with atherosclerosis." (PMID 40149646, 2025). "The CCL2-CCR2 axis, formed by the binding of CCR2 with CCL2, is associated with the progression of various diseases, such as atherosclerosis, diabetes, and cancer." (PMID 40535169, 2025). "In early atherosclerosis, only Ccl2 mRNA, encoding monocyte chemoattractant protein 1, was overexpressed in the carotid bifurcation compared with the common carotid." (PMID 38270847, 2024). "Unexpectedly, we found increased hypercholesterolemia and atherosclerosis in mice with SMC-specific deficiency of Ccl2 compared with wildtypes littermates." (PMID 38234375, 2024). "To test the potential causal role of this, we studied atherosclerosis in mice with SMC-specific conditional knockout of Ccl2." (PMID 38234375, 2024). "In a murine model of atherosclerosis, blockade of Notch signaling reduced atherogenesis, associated with diminished CCL2 expression and suppressed NF-κB activation in atherosclerotic lesions." (PMID 37061736, 2023). "CCL2 stimulates the expression of collagen by fibroblasts and is implicated in renal fibrosis, ischemic cardiomyopathy, atherosclerosis, and pancreatitis." (PMID 37524866, 2023). "CCL2 is intimately associated with unstable atherosclerosis as upregulated based on inflammatory stimuli." (PMID 36720935, 2023). "Numerous investigations conducted on animals have shown that CCL2 levels are correlated with an increased risk of atherosclerosis." (PMID 36703734, 2022). "CCL2 has been implicated as a key agonist for monocyte recruitment, which enhances the occurrence and progression of atherosclerosis." (PMID 35990936, 2022). "Accordingly, mice deficient in CCL2 are more resistant to the development of atherosclerosis in response to a high cholesterol diet than their wild type littermates." (PMID 35711383, 2022). "Plasma levels of CCL2 have been shown to be associated with an increased risk for heart failure, atherosclerosis, and coronary heart disease." (PMID 36498974, 2022). "CCR2 is necessary for the development of atherosclerosis, as it has been demonstrated in murine models of atherosclerosis where either the CCR2 gene or the CCL2 gene, encoding for one of its ligands, are inactivated." (PMID 35711383, 2022). "CCL2 is a chemokine that mediates peripheral blood monocytes recruit into the arterial wall, resulting in neointima formation in atherosclerosis, and CCL2 deficiency reduces atherosclerotic plaque formation in mice of diverse genetic backgrounds." (PMID 35990936, 2022). "The main cluster populated by the Oasl1−/−Apoe−/− mouse group (EC Sub-cluster 4) showed increased expression of genes associated with pulmonary hypertension and atherosclerosis, including Selp, Edn1, Ctla2a, Ccl2, Mmrn1, Plvap, and Lgmn." (PMID 36333342, 2022). "One study revealed that mitochondrial ROS generated by activated macrophages stimulated the expression of IL-1β, TNF-α, and CCL-2, thereby increasing the risk of developing high-fat-induced insulin resistance and atherosclerosis." (PMID 36558562, 2022). "In a cohort of 2270 patients with acute coronary syndromes, increased CCL2 levels were found to be associated with an increased risk of atherosclerosis and mortality of myocardial infarction." (PMID 33540898, 2021). "CCL2 is implicated in pathogeneses of several diseases characterized by monocytic infiltrates, such as psoriasis, rheumatoid arthritis, and atherosclerosis." (PMID 33540898, 2021).
atherosclerosis (continued). "MCP-1 (CCL-2) has been associated with atherosclerosis via increasing foam cell load in the intima of the blood vessels." (PMID 34867460, 2021). "CCL2, CCL7, and CCL12 are major chemoattractants for monocytes and CCL2 deficiency has been reported to result in attenuated accumulation of macrophages in an atherosclerosis model." (PMID 31341173, 2019). "Expression of key chemokines previously linked to atherosclerosis, including CCL2 and CXCL10 as well as CCL5, was significantly attenuated by AVE0991 treatment, in the PVAT of ApoE−/− mice, while no change was seen in the aortic wall itself." (PMID 27935022, 2017). "Of note, mice genetically deficient for CCL2 or its receptor CCR2 are protected from vascular lesions in a number of atherosclerosis models." (PMID 28661459, 2017). "To date, the CC-chemokine family has been strongly implicated in atherosclerosis with a host of CC-chemokines including MCP-1 (CCL2), RANTES (CCL5) and MIP-1α (CCL3) detected in human atherosclerotic lesions." (PMID 28282403, 2017). "CCL2 is implicated in the pathogenesis of several diseases, such as psoriasis, rheumatoid arthritis, and atherosclerosis, which are characterized by monocytic infiltrates." (PMID 28976997, 2017). "CCL2 is regarded as a risk factor for the initiation and progression of atherosclerosis and for patients with CHD." (PMID 27458015, 2016). "Deficiency of Bcl6 in bone-marrow cells of LDL receptor-deficient mice substantially promotes atherosclerosis by increasing CCL2 expression." (PMID 26001902, 2015). "Both MMP9 and CCL2 are associated with atherosclerosis where CCL2 attracts monocytes that mature into macrophages and produce MMP9." (PMID 25978399, 2015). "Increased levels of CCL2 were found to correlate with complications associated with atherosclerosis, including ischemic stroke, myocardial infarction, and cardiovascular disease mortality." (PMID 25878716, 2015). "CCL2 displays chemotactic activity for monocytes and basophils which has been implicated in the pathogenesis of atherosclerosis which is characterized by monocytic infiltrates." (PMID 24079748, 2013). "MCP-1/CCL2 is associated with coronary risk factors in sub-clinical atherosclerosis and is a predictor of cardiovascular mortality in middle-aged obese patients." (PMID 23936148, 2013). "CCL2/MCP-1 overexpression is also associated with a variety of disease states, including atherosclerosis and ischemic stroke." (PMID 22339770, 2012). "Another member of the CXC subfamily of cytokines, CCL2, has been implicated in the pathogenesis of diseases characterized by infiltrating monocytes including psoriasis, rheumatoid arthritis and atherosclerosis." (PMID 17286612, 2007). "Others have shown that macrophages and vascular smooth muscle infected by or exposed to Cpn release CCL2, which could cause vascular inflammation that can contribute to the development of atherosclerosis." (PMID 40584180, 2025). "C–C motif chemokine ligand 2 (CCL2) is a pro-inflammatory chemokine secreted by multiple cell types, which is central in the recruitment of monocytes to tissues and has a clear causal role in atherosclerosis." (PMID 38234375, 2024). "CCL2 is also implicated in the regulation of circadian rhythms during atherosclerosis progression." (PMID 39850880, 2024). "Furthermore, the atherosclerosis plaque burden was associated with increased levels of monocyte chemoattractant protein-1 (MCP-1/CCL2) in ART-treated PLWH." (PMID 38247848, 2024). "Additionally, elevated serum CCL2 levels were associated with multiple sclerosis (MS), rheumatoid arthritis (RA) and atherosclerosis." (PMID 35937499, 2022). "However, consistent with our recognition that cross-sectional studies do not allow for causal inference, this study cannot explain the cause-and-effect role of CCL2 in human atherosclerosis." (PMID 36110847, 2022).
atherosclerosis (continued). "Moreover, it has been demonstrated that CCL2/MCP-1 is strongly associated with atherosclerosis and cardiovascular diseases (CVD) in patients with SLE." (PMID 34180358, 2021). "For example, vascular smooth muscle cells senescence can promote atherosclerosis and plaque vulnerability; senescence can also up-regulate the secretion of interleukin 6 (IL-6) and CCL2 production in aortic smooth muscle cells, causing chronic inflammation and promoting atherosclerosis." (PMID 33897463, 2021). "Moreover, CCL2 is considered as a risk factor for the promotion of atherosclerosis and for patients with CAD." (PMID 30961613, 2019). "Therefore, we propose that CCL2 is a risk factor for atherosclerosis through the impairment of endothelial HDL uptake and cholesterol efflux." (PMID 27458015, 2016). "Notably, deficiency of TLR4 in apolipoprotein E-deficient mice is associated with lower CCL2 serum levels, reduced atherosclerosis and macrophage infiltration." (PMID 26001902, 2015). "Likewise, miR-467b in macrophages protects apolipoprotein E-deficient mice from atherosclerosis, likely through decreasing both plasma and lesional CCL2 levels, and through suppression of lipoprotein lipase." (PMID 26001902, 2015). "Although the number of circulating monocytes correlates with the development of atherosclerotic plaques and with the content of monocytes/macrophages in the lesions, the causal relationship between CCL2-mediated monocytosis and accelerated atherosclerosis warrants further clarification." (PMID 26001902, 2015). "Therefore, the present study aimed to investigate the potential role of H2S in atherosclerosis and the underlying mechanism with respect to chemokines (CCL2, CCL5 and CX3CL1) and chemokine receptors (CCR2, CCR5, and CX3CR1) in macrophages." (PMID 22815945, 2012). "Notably, there is an increase in CCL2 expression associated with both aging and atherosclerosis." (PMID 39201480, 2024). "Another study that transplanted visceral fat from young donor mice directly onto the carotid artery of young ApoE−/− mice, a murine model of atherosclerosis, found that the fat transplant enhanced atherosclerosis within the carotid artery, a phenotype associated with increased serum CCL2 levels." (PMID 36683460, 2023). "Since CCL2 is responsible for sustaining cellular recruitment, its prolonged or continuous release may induce pathogenic, chronic inflammatory reactions as the one seen in multiple sclerosis, atherosclerosis, and rheumatoid arthritis." (PMID 36011581, 2022). "In according to this, atherosclerosis models like CCL2 gene knock out in LDL receptor–deficient mice or CCR2 deprivation models generated by crossing mice that lack CCR2 with apo E-null mice which develop severe atherosclerosis showed a promising effect on atherosclerosis prevention." (PMID 34345249, 2021). "However, as CCL2 has been implicated in the pathogenesis of diseases characterized by monocytic infiltrates, like psoriasis, rheumatoid arthritis and atherosclerosis further investigation of rs2228467 with regard to these and related diseases is clearly warranted." (PMID 25340798, 2014). "Indeed, the chemokines growth-related oncogene (GRO)-α/CXCL1 interleukin (IL)-8/CXCL8 and monocyte chemoattractant protein (MCP)-1/CCL2 have all been implicated in the pathogenesis of atherosclerosis, at least partly through their ability to attract and activate leukocytes into the vessel wall." (PMID 22815786, 2012).
atherosclerosis (continued). "This process could be similar to the protective effect of Ccl2 and Ccr2 deficiencies for the formation of atherosclerosis that lead to a reduction of the formation of foam cells due to a reduced recruitment of systemic myeloid cells to the site of the lesion in the periphery." (PMID 22545116, 2012). "We have recently shown “that macrophages derived from LPS stimulated monocytes in individuals with subclinical atherosclerosis exhibited increased secretion of IL6, IL10 and CCL2, which was associated with intima-media thickness”." (PMID 38441018, 2025). "CC-motif chemokine ligand 2 (CCL2) is a pivotal inflammatory chemokine regulating monocyte trafficking that has been studied as a potential target in atherosclerosis." (PMID 40119478, 2025). "Research using murine models of PVAT transplantation has shown an increase in the production of PVAT-derived CCL2, which subsequently contributes to the development of atherosclerosis." (PMID 40943241, 2025). "Expression in myeloid cells accounts for a part of the atherosclerosis-promoting effect of CCL2 in mice." (PMID 38234375, 2024). "This suggests that aging enhances pro-inflammatory mechanisms, such as CCL2, thereby exacerbating the progression of atherosclerosis." (PMID 39201480, 2024). "A recent study investigating the impact of gamma irradiation on experimental atherosclerosis demonstrated consistent findings, with increased macrophage content in atherosclerotic plaques and elevated levels of CCL2, KC and MIP-2." (PMID 39088551, 2024). "In summary, CCL2 emerges as a critical mediator in age-related vascular pathologies, contributing to inflammation, arterial remodeling, and complications such as atherosclerosis, hypertension, and choroidal neovascularization." (PMID 39201480, 2024). "Classical monocytes, on the other hand, are attracted to the atherosclerosis-prone endothelium, targeted by CCL2 on the endothelial surface in a manner reliant on the leukocyte C-C Chemokine Receptor Type 2 (CCR2)." (PMID 39161593, 2024). "More specifically, these chemokines are widely recognized for their vital role in the recruitment of monocytes (CCL2), neutrophils (CXCL5/6), and lymphocytes (CXCL10), which have all been implicated in the pathogenesis of atherosclerosis." (PMID 39201392, 2024). "Curiously, overexpressing Glut1 on smooth muscle cells increases their CCL2 production which promotes monocyte recruitment and atherosclerosis progression." (PMID 39424804, 2024). "The ability of rapamycin to inhibit mTORC1 signaling and subsequently reduce CCL2 production, cell migration, and dendritic cell maturation suggests its potential as a therapeutic agent for managing atherosclerosis." (PMID 39408711, 2024). "Their important role in atherogenesis is confirmed in murine knock-out models of CCR2 and CCL2, which show a significant reduction in atherosclerosis formation compared to wild type mice." (PMID 39161593, 2024). "Blocking Ccl2 activity in mice with advanced atherosclerosis reduced further plaque progression and changed plaque composition to contain fewer macrophages, more SMCs, and more collagen." (PMID 38234375, 2024). "Previous work has shown a role of CCL2, a key chemokine governing monocyte trafficking, in atherosclerosis." (PMID 37645892, 2024). "CCL2-dependent monocytes recruitment to the atherosclerotic plaque is prominently involved in atherosclerosis progression and development of complications." (PMID 38975335, 2024). "In the present study, we assessed the importance of SMC-secreted CCL2 for early atherosclerosis in murine atherosclerosis induced by PCSK9 overexpression." (PMID 38234375, 2024). "Deletion and Inhibition of CCL2: Studies have demonstrated that the deletion of CCL2 can reduce macrophage accumulation in conditions such as atherosclerosis." (PMID 39201480, 2024). "Conversely, the overexpression of Ccl2 in ApoE−/− mice resulted in the acceleration of atherosclerosis." (PMID 38794213, 2024).